CGAS (cyclic GMP-AMP synthase)
Diseases named in the same sentence as CGAS in open-access papers (continued):
Sharing a sentence is not in itself a finding about the gene and the disease.
viral infection (continued). "Although many factors involved in viral infection and anti-viral response have been identified, such as cGAS/STING and JAK/STAT pathways, the virus-host interaction is still not fully clear." (PMID 38829910, 2024). "Phosphorylation and ubiquitination of STING were also observed during viral infection, confirming that NiV and MeV activated the cGAS–STING signaling pathway." (PMID 38525112, 2024). "During viral infection, cGAS can be cleaved by apoptotic caspase‐3, leading to the inactivation of cGAS catalytic activity and weakened cGAMP production." (PMID 39287214, 2024). "With the deepening of research, multiple functional roles and specific mechanisms of cGAS-STING during viral infections were identified, especially its effects on inflammation, oxidative stress and cell death." (PMID 38426093, 2024). "The cGAS-STING pathway is essential for defending against viral infections and maintaining cellular balance." (PMID 38765007, 2024). "Antiviral responses induced by cGAS are inhibited by a deficiency in Uaf1 and inhibitors of the UAF1-USP1 deubiquitinase complex, thus promoting viral infection." (PMID 39183465, 2024). "The NF-κB transcription factor plays a crucial role in coordinating inflammatory responses induced by cGAS-STING during viral infections." (PMID 39599510, 2024). "We found that ARID1B-deficient cells exhibited activation of the cGAS-STING signaling pathway 31-39, which is involved in the innate immune response to DNA damage and viral infection." (PMID 38577613, 2024). "Viral infection eventually destroys homeostasis in the host cell, and exposure to increasing DNA concentrations activates the cGAS–STING signaling pathway quickly." (PMID 38525112, 2024). "Along with viral infections, cGAS/STING signaling is critical for generating a protective immune response against bacterial, parasitic, and fungal infections to maintain immune homeostasis." (PMID 38339107, 2024). "It is well known that NF-κB is the predominant regulator of inflammation and cGAS-STING can drive NF-κB activity during viral infections." (PMID 38426093, 2024). "Mn2+ is released from mitochondria and the Golgi apparatus upon virus infection and accumulated in the cytosol where it is bound to cGAS, enhancing the sensitivity of cGAS to dsDNA and its enzymatic activity." (PMID 38612580, 2024). "Despite the involvement of cGAS in antiviral responses, little is known about its ability to restrict duck-origin virus infection." (PMID 36733488, 2023). "Mislocalization of cGAS to cytosolic or nuclear compartments induces genotoxic stress but weaker responses to viral infection." (PMID 36754281, 2023). "The reduced level of IRF-activating kinases is associated with a weaker type I IFN response downstream of RLR and cGAS activation, which likely explains the enhanced susceptibility of patients with TBK1 mutation to severe viral infection." (PMID 36936901, 2023). "The cyclic GMP-AMP synthase (cGAS) pathway, a crucial component of the innate immune response, is responsible for identifying viral infections and triggering antiviral reactions by activating the cGAS-STING pathway." (PMID 37376520, 2023). "Targeting viral proteins involved in the suppression of the cGAS-STING pathway remains an underexplored approach for the treatment of tumors induced by viral infections." (PMID 38139802, 2023). "The Mn2+ ion is released from membrane-enclosed organelles upon viral infection and accumulates in the cytoplasm where it binds directly to cGAS." (PMID 36851604, 2023). "In recent years, increasing evidence has suggested that RNA viruses, such as DENV, ZIKV, EMCV, and IAV, can activate the cGAS-STING signaling pathway during viral infection." (PMID 36745686, 2023). "Viral infection triggers cGAS-STING signaling pathway that induces activation of type I IFN and NF-κB signaling to restrict viral infection and to sustain homeostasis." (PMID 36825026, 2023).
viral infection (continued). "A study has observed that cGAS is not only present in the cytoplasm but also in the nucleus and that nuclear cGAS plays a role in innate immunity against viral infections by regulating histone arginine modification." (PMID 37600809, 2023). "During viral infections, viral replication induces the responses of inflammatory factors and ISGs, and the cGAS-STING pathway is activated, subsequently inhibiting the progression of viral infection." (PMID 37600809, 2023). "Following viral infection, cGAS can directly trigger autophagy, and the presence of cGAMP or poly(dA:dT) can stimulate STING to induce autophagy." (PMID 38125906, 2023). "This is mainly due to the leakage of mtDNA and the abnormal activation of cGAS-STING induced by viral infection." (PMID 37492580, 2023). "Immune responses to viral infection are mediated by various cytosolic DNA- and RNA-sensing pathways, including cGAS-STING and RIG-I/MAVS." (PMID 38161589, 2023). "In fact, the cGAS-STING signaling pathway, initially identified for its role in the innate immune response against viral infections and DNA damage, has recently been implicated in the regulation of inflammation and metabolism, as confirmed by our study." (PMID 37762143, 2023). "The cGAS-STING signaling pathway can sense viral infections and induce the production of type 1 interferons (IFNs) to combat the invading pathogens." (PMID 36769349, 2023). "In terms of viral infections, DNA viruses can directly activate cGAS, whereas RNA viruses can indirectly activate cGAS through mitochondria, which is beyond the scope of this article." (PMID 37492580, 2023). "STING is a cytosolic sensor of the cyclic dinucleotide 2′3′-cyclic guanosine monophosphate–adenosine monophosphate (2′3′-cGAMP), which is produced by cyclic GMP-AMP synthase (cGAS) due to cytosolic DNA as a result of cell death or viral infection." (PMID 36910138, 2023). "The cGAS-STING signaling pathway plays a pivotal role in the host defense against viral infections, such as SARS-CoV-2 and Ectromelia Virus." (PMID 36733488, 2023). "The cGAS function in mammals has been investigated extensively; however, the function of duck cGAS (du-cGAS) in response to viral infections is still unclear." (PMID 36733488, 2023). "Various disease models, including autoimmune diseases, inflammation, organ damage and fibrosis, tumor occurrence and treatment, and viral infection, have been used in studies on modulators related to the cGAS-STING pathway." (PMID 37600809, 2023). "Double-stranded DNA generated through viral infection or cellular stress can induce the assembly of cGAS oligomers, leading to the enzymatic activation of cGAS and the production of 2′3′ cyclic GMP–AMP (cGAMP)." (PMID 38275951, 2023). "Upon viral infection, viral DNA is firstly recognized by cGAS, a cytoplasmic DNA sensor, resulting in a conformational switch in cGAS to catalyze the production of the second messenger cGAMP, then cGAMP binds to STING located on the endoplasmic reticulum." (PMID 36937252, 2023). "The cyclic GMP-AMP synthase (cGAS)/stimulator of interferon gene (STING) signaling pathway plays a critical protective role against viral infections." (PMID 38129386, 2023). "The pathway mediated by cGAS-STING activation has been shown to be key to the cell response not only to viral infections, but also to cellular stress, tissue damage and cancer." (PMID 35458396, 2022). "DNA viruses such as human papillomavirus, cytomegalovirus, adenovirus, and vaccinia virus have all been shown to activate cGAS and induce a host immune response to resist viral infection." (PMID 35185917, 2022). "Viral infection-driven cGAS-STING mediated type I IFN signaling has clearly shown the crucial role of cGAS-mediated STING activation against several DNA viruses." (PMID 35008917, 2022).
viral infection (continued). "Type I IFNs are generally turned on during viral infection after sensing of viral nucleic acids by cellular pattern recognition receptors, such as the cytosolic DNA sensor cGAS and the RNA sensor RIG-I." (PMID 36255240, 2022). "Cyclic GMP-AMP synthase (cGAS) detects cytosolic DNA during virus infection, and induces an antiviral state." (PMID 35216035, 2022). "PRV is a typical DNA virus and the cGAS-STING pathway is the major sensor for recognizing its viral DNA during virus infection." (PMID 36090064, 2022). "In this study, the researchers also observed that TRIM14 promotes cGAS enzymatic activity upon viral infection, while recruiting the deubiquitinase USP14." (PMID 36231006, 2022). "Since cGAS possibly plays a crucial role in activating cellular innate immune responses upon nuclear engagement due to viral infection, we investigated the expression levels of cGAS protein in the nuclear and cytosolic compartments." (PMID 36311756, 2022). "The study identified R124 residue as the direct catalyzing site by PRMT5; cGAS(R124K) mutant abolished PRMT5-mediated suppression of type I IFN production during virus infection." (PMID 36591232, 2022). "One report suggests that caspase-3 and -7 can cleave cGAS during apoptosis and other viral infections." (PMID 36255240, 2022). "During a viral infection, DNA is sensed by cGAS (cyclic GMP-AMP synthase) resulting in the synthesis of 2′3′-cGAMP which in turn activates STING leading to the production of IRF3 and IFN-β24,25." (PMID 36002507, 2022). "For instance, the expression level of USP29, which interacts and stabilizes cGAS, is generally low, but is upregulated upon virus infection owing to establish an antiviral state." (PMID 35008917, 2022). "Taken together, our data demonstrate that nuclear soluble cGAS can sense DNA virus infection in the nucleus, instigate innate immune response, and inhibit viral infection." (PMID 35538147, 2022). "In summary, we have demonstrated that HSV-1 infection induces the release of cGAS from the chromatin to the nuclear soluble fraction and the nuclear soluble cGAS is a nuclear DNA sensor during viral infection." (PMID 35538147, 2022). "Here, activation of cGAS (cyclic GMP AMP synthase) by viral infection or DNA from damaged mitochondria leads to production of the second messenger cGAMP (cyclic guanosine monophosphate-adenosine monophosphate)." (PMID 35766350, 2022). "2′,3′-cGAMP interacts with ASFV C129R and EP364R, and elevated intracellular and extracellular 2′,3′-cGAMP due to viral infection or overexpression of cGAS is degraded by both ASFV genes with phosphodiesterase activity." (PMID 35861515, 2022). "Our data provide a model that nuclear cGAS can sense HSV-1 infection at the early stage of viral infection." (PMID 35538147, 2022). "cGAS is an aberrant DNA sensor, which resists exogenous virus infection via the cGAS/STING signaling cascade by producing a battery of immune and inflammatory mediators, including type I and type III interferons." (PMID 36183107, 2022). "cGAS is activated by recognizing double-strand DNA, a prominent antiinflammatory response in bacterial and viral infections." (PMID 36230643, 2022). "Recent studies have reported that the inflammasome response after bacterial and viral infections is ameliorated by inhibiting the cGAS–STING–NLRP3 axis in human myeloid cells." (PMID 35642042, 2022). "Although CGAS was originally found to be required for STING1 activation during viral infection, recent studies have also reported a CGAS-independent STING1 pathway in response to different stimuli, including viral infection." (PMID 35769880, 2022). "mcGAS was found to be SUMOylated by TRIM38 at the resting state on K271/K464, which antagonizes ubiquitination-mediated degradation, resulting in cGAS stabilization for acute sensing viral infection." (PMID 35795661, 2022).
viral infection (continued). "Tripartite motif (TRIM) family proteins, as multifunctional ubiquitin E3 ligases, play a central role in host defense against viral infection, which is achieved partially by regulating the PTMs of cGAS." (PMID 34899698, 2021). "In virus infection, short viral DNAs or RNAs bind with cGAS and, consequently, with phosphorylates STING in ER lumen for activating IRF3 and NFkB transcriptional factors." (PMID 34680466, 2021). "Even RNA viruses, with much smaller genomes, encode multiple cGAS/STING/TBK1 pathway inhibitors, testifying to the importance of this pathway during viral infection." (PMID 34903048, 2021). "Since syncytium formation is a common phenomenon taking place during most viral infection, targeting syncytium formation and cGAS-STING signaling holds the promise to treat a variety of virological diseases where syncytia were induced." (PMID 34674770, 2021). "Upon viral infection and activation of systolic cyclic GMP-AMP synthase, STING mediates type I interferon (IFN-I) production by infected cells to protect them and neighboring cells from local infection." (PMID 34532061, 2021). "The pattern recognition receptor cGAS detects cytosolic DNA during viral infection and catalyzes in turn the formation of cyclic-GMP-AMP (cGAMP)." (PMID 34205379, 2021). "During the virus infection, cGAS and RIG-I are two major sensors in the recognition of viral nucleic acids, which further lead to the induction of IFN." (PMID 34471099, 2021). "DNA viruses, including adenovirus and vaccinia virus, can activate cGAS/STING, mice deficient in this pathway are more susceptive to viral infection." (PMID 34768911, 2021). "This study revealed that the cGAS–STING pathway works similarly both in virus infections and neurodegenerative diseases." (PMID 34782623, 2021). "In a coincidence sensing/co-activation model, potent activation of cGAS under physiological conditions would occur only when both increased cytosolic DNA and translation stress are sensed, such as during virus infection." (PMID 34111399, 2021). "cGAS is activated through recognition of double‐strand DNA, which is a prominent anti‐inflammatory response in bacterial and viral infections." (PMID 34010983, 2021). "Expression of ISG15 is robustly stimulated by IFNs, viral infection, DNA damage, and cGAS–STING signaling." (PMID 34884568, 2021). "Upon virus infection, cGAS is phosphorylated by DNA-dependent protein kinase (DNA-PK), hindering its oligomerization and enzymatic activity." (PMID 34966372, 2021). "In the present study, we propose that induction of antiviral priming by mtDNA via cGAS is a general response to virus infection, which can lead to the intrinsic downregulation of mitochondrial protein expression." (PMID 34648591, 2021). "Strikingly, several recent studies have reported that cGAS-like and STING-like proteins that protect bacteria against viral infection are found in bacteria, raising the possibility that the cGAS-STING pathway originates from the bacterial immune system." (PMID 35095914, 2021). "To investigate the regulatory mechanism of cGAS expression in innate immune responses against viral infection, we first infected L929 cells and MEFs with the DNA virus HSV-1." (PMID 33767433, 2021). "In cytosol, the self-DNA leaked from mitochondria, nucleus, or phagosome serves as DAMPs; while the nucleic acids, such as viral DNA or leaked mitochondrial DNA caused by viral infections serves as PAMPs, which are sensed by cyclic GMP-AMP Synthase (cGAS)." (PMID 33762743, 2021). "The cGAS‒STING signaling pathway can help the body to resist viral infection and tumor cells; however, it can also induce severe inflammation and affect autoimmunity when excessively activated." (PMID 34718659, 2021). "Upon virus infection, cytosolic DNA is recognized by DNA sensors such as cyclic GMP-AMP synthase (cGAS), which catalyzes formation of an atypical cyclic di-nucleotide second messenger 2′,3′-cGAMP." (PMID 32886065, 2020).
viral infection (continued). "cGAS is activated by cytosolic DNA, which is indicative of viral infection, to initiate a signalling cascade leading to a type I interferon response." (PMID 32674481, 2020). "The cGAS-STING pathway is immensely important for controlling viral infection and many viruses have developed methods to inhibit this pathway." (PMID 32669552, 2020). "There are several cytosolic dsDNA sensors involved in the host cells innate immunity against viral infections, including cGAS, whose secondary messenger cyclic GMP-AMP (cGAMP) can activate downstream sensor protein stimulator of IFN genes (STING)." (PMID 33664729, 2020). "The deficiency of cGAS and STING points to the existence of alternative mechanisms of controlling cytoplasmic DNA-associated cell damage and viral infections in pangolins." (PMID 32533513, 2020). "After DNA transfection, cGAS translocates to the cytoplasm and forms large foci (probably liquid droplets of cGAS-DNA complex), to respond to extraneous DNA and viral infection." (PMID 32714322, 2020). "cGAS is popularly known to (a) act as cytosolic sensors for free nucleic acid or micronuclei during bacterial/viral infections and (b) trigger immune response by activating cGAS‐STING signaling." (PMID 32979859, 2020). "A recent study discovered that chicken IRF7 constitutes IRF3 to mediate the relevant signaling function; thus, like in mammals, the chicken cGAS-STING-TBK1-IRF7 signaling pathway plays a critical role in circumventing virus infection." (PMID 32660114, 2020). "Cyclic GMP-AMP (cGAMP) synthase (cGAS) is an intracellular sensor of cytoplasmic viral DNA created during virus infection, which subsequently activates the stimulator of interferon gene (STING)-dependent type I interferon response to eliminate pathogens." (PMID 32933581, 2020). "BRD4 inhibition also de-compacted chromatin structure and induced the DNA damage response, thereby triggering the activation of cGAS-mediated innate immunity and increasing host resistance to viral infection both in vitro and in vivo." (PMID 32208449, 2020). "Except for the pivotal role of cGAS in virus infection, cGAS is important for maintaining homeostasis in several cells." (PMID 33243993, 2020). "HSV-1 tegument proteins UL24 and UL42 were found to bind to the endogenous NF-κB subunits p65 and p50, abrogating their nuclear translocation and NF-κB activation downstream of the cGAS-STING signaling pathway during viral infection." (PMID 32714322, 2020). "STING plays a crucial role in various diseases, inactivation of cGAS-cGAMP-STING function is reported to be associated with many severe diseases such as cancer, obesity, liver injury, sugar-lipid metabolism and virus infection and etc." (PMID 31120925, 2019). "Previous work showed that caspase inhibition in the context of viral infection increases constitutive IFN production via the STING/cGAS pathway." (PMID 29786074, 2019). "Loss of cGAS in various cell lines and also in vivo results in a complete loss of type I IFN induction upon DNA delivery or viral infections." (PMID 31426357, 2019). "Signaling via STING and the dsDNA sensor cGAS has emerged as an important cellular defense against viral infection." (PMID 30134546, 2018). "2′3′-cGAMP is produced by cGAS upon viral infection in host cells, whereas 3′3′-cGAMP is a bacterial second messenger recognized by STING as an external PAMP." (PMID 30356045, 2018). "Given the central role of the cGAS pathway in the innate immune response to viral infections, it is expected that various modulations and modifications to cGAS control its activity." (PMID 29426904, 2018). "Further, knockdown of cGAS is capable of rescuing the growth defect of UL31-deficient viral infection, indicating that the UL31/cGAS interaction has implications for overall viral growth." (PMID 30134546, 2018).